MTOR (mechanistic target of rapamycin kinase)
Diseases named in the same sentence as MTOR in open-access papers (continued):
Sharing a sentence is not in itself a finding about the gene and the disease.
breast cancer (continued). "Hence, investigating the relationship between ZRF1, the mTOR pathway and the senescence program will help to better understand cell death regulation in breast cancer cells." (PMID 29983888, 2018). "In addition, OC also induced significant inhibition of the mammalian target of rapamycin (mTOR) of which abnormal activation supports the proliferation of breast cancer cells among other cancers and neurologic diseases." (PMID 30250008, 2018). "In addition, we have identified a novel SMYD2 transcriptional target gene, PTPN13, which links SMYD2 to other known breast cancer associated signaling pathways, including ERK, mTOR, and Akt signaling via PTPN13 mediated phosphorylation." (PMID 29487338, 2018). "Importantly, RET expression in breast cancer is also correlated with resistance to endocrine therapies via stimulation of the mTOR signaling pathway." (PMID 30666215, 2018). "However, PI3K/AKT signaling activation was inhibited by mTOR in breast cancer, indicating differential effect of mTOR in different type of cancers." (PMID 30618730, 2018). "Additional molecular alterations such as somatic PIK3CA mutations, part of the PI3K/AKT/mTOR pathway, are commonly identified in breast cancers but are not yet used in the selection of approved therapies." (PMID 29177603, 2018). "The possible mechanisms might be that RA inhibited the SRC/AKT signaling pathway in osteoclasts as well as AKT/mTOR signaling in breast cancer cells." (PMID 29515110, 2018). "In conclusion, our results suggest that combining mTOR and DNA repair inhibition could be a successful strategy to treat a subset of breast cancer with BRCA2 mutation and alterations in the PI3K/AKT/mTOR pathway." (PMID 30038706, 2018). "We next investigated whether mTOR signaling is also involved in the SALL1-induced breast cancer growth inhibition and senescence induction." (PMID 29625565, 2018). "Further investigation addressing the interplay between ZRF1 and mTOR inhibitors might provide valuable information regarding the endocrine resistance in breast cancer cells." (PMID 29983888, 2018). "Thus, TFEB is most likely not involved in the regulation of the ErbB2-induced, invasion-promoting lysosomal alterations in breast cancer cells, since ErbB2 activation leads to the activation of the mTOR and MAPK-ERK signaling pathways." (PMID 29396433, 2018). "The present findings suggest that the combination of mTOR and PARP inhibitors could represent a promising therapeutic approach for the treatment of BRCA2 mutated breast cancers." (PMID 30038706, 2018). "In breast cancer cells it was shown that E2 might activate mTOR via small GTPase Ras homolog enriched in brain (Rheb), and it is still unclear how E2/ER signaling interacts with Rheb63." (PMID 29472585, 2018). "In the present study, the suppressive effect of delphinidin on HER-2 positive breast cancer cells was shown to occur through the mTOR pathway; thus, the proliferation inhibition and autophagy induced by delphinidin might be attributable to the same pathway." (PMID 29587684, 2018). "Also, inhibition of mTOR by rapamycin can up-regulate TAp73 expression and synergize cisplatin sensitivity in basal-like breast cancer cells through a TAp73-dependent manner." (PMID 29535821, 2018). "ARD1 was reported to inhibit mTOR activity to limit breast cancer cell growth." (PMID 30154412, 2018). "Similarly, mTOR inhibition also increases TAp73 expression and synergizes cisplatin sensitivity in basal-like breast cancer cellsthrough a TAp73-dependent manner." (PMID 29535821, 2018). "Taken together, these results suggest that MASTL overexpression correlates with deregulation of desmosomes, actin regulatory proteins, disruption to PI3K/AKT/mTOR signalling and an increase in DNA damage signalling across patient tumour samples, breast cancer cell lines and our MCF10A model system." (PMID 29743597, 2018). "The abnormal expression of mTOR is illustrated in breast cancer cells." (PMID 29300316, 2018).
breast cancer (continued). "Others have been recently approved for the treatment of specific breast cancer subtypes, such as the mTOR inhibitor everolimus in advanced luminal breast cancer and the poly(ADP-ribose)polymerase (PARP) inhibitor olaparib in metastatic breast cancer with germline BRCA1 or BRCA2 mutations." (PMID 30038706, 2018). "Glioblastoma multiforme (GBM), renal carcinoma and breast cancer cells treated with Nutlin-3 entered senescence in a mechanism that may be dependent on active mTOR." (PMID 29805774, 2018). "Also the combination treatment of honokiol and mTOR inhibitor would be capable of treatment of breast cancer." (PMID 29311925, 2017). "We observed synergy of CB-839 with the highly potent mTOR catalytic site inhibitor in breast cancer cell lines suggesting that therapeutic strategies for GLS inhibitors may include combinations with drugs targeting modulators in both pathways." (PMID 28950000, 2017). "Altogether these findings indicate that downregulation of miR-21-5p expression by metformin, followed by release of CAB39L and SESN1, contributed to attenuating the mTOR aberrant activity and rendering breast cancer cells more prone to cell death induced by a clinically relevant mTOR inhibitor." (PMID 28698800, 2017). "In tamoxifen resistant ER-positive breast cancer cell line, aspirin might also inhibit the upstream regulators of c-myc and cyclinD1 proteins, such as the mTOR signaling, wnt/β-catenin and NF-κB pathways." (PMID 28415819, 2017). "Our analysis of the cellular responses to either GLS knockdown or pharmacological inhibition has identified potential PD markers and provides a molecular basis for combining GLS and mTOR inhibitors as a novel therapeutic strategy for treating basal breast cancers." (PMID 28950000, 2017). "In earlier studies we have shown that CCL5 activation of CCR5 induces the proliferation and survival of breast cancer cells in a mechanistic target of rapamycin (mTOR)-dependent manner and that this is in part due to CCR5-mediated increases in glycolytic metabolism." (PMID 29216863, 2017). "Besides, the Ras/PI3K/PTEN/Akt/mTOR cascades were found involved in chemo and hormonal resistance in breast cancer as the constitutively activated Akt-1 gene was more resistant to doxorubicin, etoposide, and 4-OH-tamoxifen." (PMID 28827892, 2017). "Likewise, inhibition of mTOR after rapamycin treatment of MCF‐7 breast cancer cells leads to increased AMPK activation, indicating a reciprocal relation between these energy‐sensing pathways." (PMID 27660040, 2017). "Researchers in a number of preclinical studies have previously linked mTOR signaling to bone biology; however, assessment of mTOR inhibition in bone biology in the context of osteotropic breast cancer has not been performed in detail." (PMID 28793923, 2017). "Metformin-induced inhibition of the mTOR pathway has been demonstrated in different types of cancer, such as leukemia, lung cancer, breast cancer, oral squamous cell carcinoma, lymphoma, and thyroid cancer in human, as well as in both papilloma and squamous cell carcinoma in mice." (PMID 28126011, 2017). "As CPT inhibition of mTOR pathway is independent on affecting the mTOR complex in breast cancer cells, it may be due to interference of mTOR upstream." (PMID 28272775, 2017). "In this context, we report here the results of in vitro and in vivo investigation to test the utility of 111In-bevacizumab in the detection of the response to the anti-angiogenic mTOR inhibitor rapamycin, analogues of which (everolimus) are used to treat renal and breast cancer." (PMID 28560583, 2017). "The mTOR signalling has high clinical relevance in human prostate and breast cancers." (PMID 28615679, 2017). "However, the effect of mTOR inhibitors on tumour vasculature in patients with renal and breast cancer remains unexplored." (PMID 28560583, 2017). "The mTOR pathway is frequently upregulated in breast cancer specimens." (PMID 28451590, 2017).
breast cancer (continued). "Overall, CPT is a natural anti‐oestrogen agent and could inhibit ERα‐mediated IGF‐1/AKT/mTOR pathway to increase the sensitivity of the ERα‐positive resistant breast cancer cells." (PMID 28272775, 2017). "Our data suggest that a combination of Akt and mTOR inhibitors have greater antitumor activity in breast cancer cells, which may be a viable approach to treat patients." (PMID 28991258, 2017). "We reviewed the functional properties of the driver nodes found to have the highest impact in controlling the essential proteins; they are ERBB2, SRC, PDPK1, PRKDC, mTOR for breast cancer, ERBB2, AKT1, GSK3B, ABL1 in pancreatic cancer, and RET in ovarian cancer." (PMID 28871116, 2017). "Therefore, the synergistic effect on breast cancer cells is connected with further inhibition of the PI3K/mTOR signalling pathway." (PMID 28060760, 2017). "Previous studies suggested that mTOR inhibitors may have favorable effects in antiestrogen resistant breast cancer compared with the AI resistant counterpart." (PMID 29137418, 2017). "Based on the observations of the study it was hypothesized that greater degree of the reticence of PI3K/Akt/mTOR pathway mediated by mTOR inhibitor intensified the sensitivities of the cells of breast cancer to honokiol." (PMID 29311925, 2017). "There have been several reports that UCA1 affected AKT expression and the activity of the PI3K-Akt-mTOR signaling pathway in the progression of bladder carcinoma cells, prostate cancer, breast cancer and non-small cell lung cancer, but similar studies of gastric cancer have not been reported." (PMID 29212166, 2017). "We next investigated whether AMPK/mTOR pathway was involved in BME induced autophagy in breast cancer cell lines." (PMID 29029506, 2017). "This fact could suggest that non cytotoxic drugs (as letrozole in breast cancer, for example) are better combinations of mTOR inhibitors than cytotoxic chemotherapy." (PMID 28484222, 2017). "In response to the mitochondrial dysfunction previously shown to be induced by buformin, we observed concomitant upregulation of p-AMPK and downregulation of p-mTOR and downstream targets, p-p70S6K and p-4EBP1, in erbB-2-overexpressing breast cancer cells in vitro." (PMID 28193239, 2017). "For this reason, we analysed MDM4 and mTOR in the database of human breast cancer." (PMID 28270148, 2017). "SFN, one of the best characterized ITC present in high concentrations in broccoli, decreased phosphorylation of Akt and S6K1 in MDA-MB-231, MCF-7, MDA-MB- 468 and SKBR-3 breast cancer cell lines and inhibited Akt and mTOR pathway in acute lymphoblastic leukemia cells." (PMID 27154770, 2017). "For the mTOR pathway, radiation could cause decreased phosphorylation of the autophosphorylation site of p-mTOR (decreased p-mTOR/mTOR ratio) in an in vitro study of MCF-7 breast cancer cell line." (PMID 28320471, 2017). "Other studies also indicated that APS can prevent tumor growth through down-regulation of the expression of Akt phosphorylation in human breast cancer cells, modulation of both mTOR and ERK signaling pathways or Caspase 3 activation in human colon cancer cells." (PMID 29225515, 2017). "Highly transformed breast cancer cells orchestrate a varety of complex responses to survive hypoxic conditions, allowing, for example, uninterrupted protein synthesis via constitutively activated mechanistic target of rapamycin (mTOR) signaling." (PMID 28320353, 2017). "The inverse correlation between MDM4 and mTOR observed in human breast cancer specimens is in agreement with this hypothesis." (PMID 28270148, 2017). "Besides the different cell proliferation in vitro and cell growth in vivo, the related proteins of mTOR pathway were also found to express differently in two types of breast cancer cells." (PMID 28272775, 2017). "Interestingly, in human breast cancer cell lines and primary breast tumors, there exists a reciprocal correlation between FBW7 loss and PTEN loss, which also activates mTOR." (PMID 28036276, 2017).
breast cancer (continued). "IGFs and the IGF1R are possibly involved in the cellular response to Herceptin, as they may activate the Akt/Bad and mTOR signaling pathways in breast carcinoma cells." (PMID 28507201, 2017). "We next assessed whether inhibition of mTOR activity in breast cancer cells impacts mTOR degradation." (PMID 27748082, 2016). "Estrogens, particularly its predominant form E2, could inhibit mTOR activation in osteoblasts, and phytoestrogens calycosin and liquiritigenin also inhibited the activation of mTOR pathway in breast cancer cells and glioma cells, respectively." (PMID 27863380, 2016). "Subsequent laboratory studies have focused on comparison of everolimus in combination with endocrine therapies as well as other PI3K/Akt/mTOR inhibitors in a variety of breast cancer cell lines and these studies have reported synergy between tamoxifen or AI therapy and everolimus." (PMID 27421652, 2016). "Therefore, it is clinically important that, compared to metformin, MFB markedly activated AMPK and inactivated mTOR with greater potency in all tested breast cancer cells in vitro and in vivo." (PMID 27223262, 2016). "However, alisol B has been reported as a new autophagy inducer functioning through activation of CaMKK/AMPK/mTOR signaling, induction of apoptosis and triggering of cell death in breast cancer cells." (PMID 26999089, 2016). "In contrast, whereas a 70 % decrease in S6 phosphorylation at Ser235/236 was observed in parental cell lines, a smaller 20 % decrease occurred in resistant cells suggesting that sustained mTOR activity leads to BYL719 resistance in PIK3CA mutant breast cancer cells." (PMID 27048245, 2016). "In earlier studies, we showed that CCL5 enhances proliferation and survival of MCF-7 breast cancer cells in an mTOR-dependent manner and we provided evidence that, for T cells, CCL5 activation of CCR5 results in increased glycolysis and enhanced ATP production." (PMID 27335323, 2016). "Given the prevalence of PI3K/AKT/mTOR pathway alterations in patients with breast cancer and the availability of several inhibitors of this pathway, this coexistence of molecular alterations may be an important biomarker." (PMID 27489863, 2016). "To experimentally test whether mTOR plays a role in miR-100-mediated sensitivity to paclitaxel, we first measured mTOR protein expression in the 6 luminal A and basal-like breast cancer cell lines used for expression and functional analyses of miR-100." (PMID 26744318, 2016). "mTOR plays an important role in pathogenesis and therapy resistance in breast cancer." (PMID 27015560, 2016). "In this study, we analyzed PI3K pathway activation in 67 patient-derived xenografts (PDX) of breast cancer and investigated the anti-tumor activity of the mTOR inhibitor everolimus in 15 TNBC PDX with different expression and mutational status of PI3K pathway markers." (PMID 27374081, 2016). "One of the potential mechanisms of the ensuing drug resistance in breast cancer is the upregulation of mTOR pathway, which may involve increased activity or increased levels of total proteins in the mTOR pathway." (PMID 27748082, 2016). "Importantly, for the first time, synergistic inhibition is demonstrated when combining IGF-1R and mTOR targeting agents in breast cancer cells." (PMID 27765027, 2016). "In contrast, analysis of divergent breast cancer cell lines revealed that mutations in PIK3CA but not PTEN loss coincide with increased sensitivity to mTOR inhibitors." (PMID 26814435, 2016). "In conclusion, we synthesized trisubstituted imidazoles, identified the bioactive cytotoxic lead structure, predicted the likely target and demonstrated in vitro efficacy of lead compound to abrogate the activation of the PI3K/Akt/mTOR pathway in human breast cancer cells." (PMID 27097161, 2016). "Moreover, investigating efficacy of mTOR-KIs in metastatic breast cancer patients are reported (e.g. NCT02216786, NCT02049957)." (PMID 27015560, 2016).
breast cancer (continued). "APA also inactivated the Akt/mTOR pathway in breast cancer cells." (PMID 26943775, 2016). "We have detected defective proteolysis of mTOR protein in breast cancer cells, which could, at least in part, explain the high level of mTOR protein in these cells." (PMID 27748082, 2016). "THBS1 and TNC in the tumor microenvironment may bind to and activate integrin β1 on the surface of breast cancer cells to phosphorylate intracellular mTOR pathway." (PMID 27487140, 2016). "Notably, feedback upregulation of the mTOR pathway is one of the potential mechanisms of drug resistance in breast cancer." (PMID 27748082, 2016). "Since activation of AMPK causes inhibition of mTOR 45, 46, 47, our finding raises the possibility that AMPK–mTOR signaling event might also be involved in breast cancer cell growth inhibition." (PMID 27748082, 2016). "Furthermore, an additive antitumor effect on breast cancer cells was observed when combining mTOR inhibitors with histone deacetylases (HDACs)." (PMID 26536665, 2016). "Interestingly, PI3K/AKT/mTOR pathway activation is also required for the viability and maintenance of breast cancer stem cells." (PMID 26869349, 2016). "Phytoestrogen calycosin and ERβ agonist liquiritigenin could up-regulate ERβ expression and inhibit the activation of mTOR pathway in breast cancer cells and glioma cells, respectively." (PMID 27863380, 2016). "However, in breast cancer, mTOR inhibition by metformin also blocks glycolytic and tricarboxylic acid cycle intermediates necessary for cancer proliferation, thus interfering with the Warburg effect." (PMID 27391065, 2016). "If mTOR-ACL hyperactivation plays a role in HER2+/PIK3CAmut breast cancer cell survival, they might be particularly sensitive to mTOR-KI treatment." (PMID 27015560, 2016). "To evaluate whether mTOR is a target molecule of miR-100 in breast cancer, we collected breast cancer samples in the TCGA database that had expression information for both miR-100 and mTOR protein, and looked for correlations between their expression levels." (PMID 26744318, 2016). "In addition to ER mutation, activation of the mTOR pathway has been shown to promote acquired resistance to endocrine therapy, leading to the use of mTOR inhibitors such as everolimus in advanced breast cancer." (PMID 27472462, 2016). "mTOR signaling is frequently activated in HER2/neu-positive breast cancer cells and tumors and may contribute to the lipotoxicity observed in HER2/neu-positive SKBR3 cells." (PMID 27464732, 2016). "The high level of total mTOR protein in the breast cancer cells could be attributed to increased expression and/or reduced degradation of mTOR protein." (PMID 27748082, 2016). "Moreover, aberrant activation of both PI3K/Akt/mTOR and MAPK/ERK signalling pathways has been associated with resistance to conventional therapy in breast cancer, including both chemotherapy and endocrine therapy." (PMID 26565813, 2016). "However, toxicity is a limiting factor that precludes the use of high doses of mTOR inhibitors, particularly rapalogs, in combinatorial treatment for breast cancer." (PMID 27748082, 2016). "One of such mechanisms is the upregulation of mTOR pathway in breast cancer cells." (PMID 27748082, 2016). "In breast cancer, mutations in individual components in the PI3K/Akt/mTOR pathway are more frequent than in the MAPK/ERK pathway, and this may be one reason why earlier effects were seen in the PI3K/Akt/mTOR pathway relative to the MAPK/ERK pathway." (PMID 26565813, 2016). "While it is increasingly recognized that de novo lipid synthesis is an important aspect of cancer metabolism, elucidating the role and mechanism of mTOR pathway in this process, particularly in breast cancer molecular subtype, may aid therapeutic strategy." (PMID 27563814, 2016). "Furthermore, statistical gene-environment interactions between mTOR SNPs and BMI were verified in esophageal squamous cell carcinoma and breast cancer." (PMID 27462867, 2016).